MIR890 (microRNA 890)
Synonyms: hsa-mir-890; MIRN890
Gene: MicroRNA gene on chromosome X (145,994,275 to 145,994,351, reverse strand). Ensembl gene ENSG00000216075.
Homologues: Orthologues: chimpanzee ptr-mir-890 (100% identical).